IL10 (interleukin 10)
Diseases named in the same sentence as IL10 in open-access papers (continued):
Sharing a sentence is not in itself a finding about the gene and the disease.
Allergy (continued). "Downstream abnormalities in allergen-specific Treg cells involving immunomodulatory cytokines, including IL-10 and TGF-β, may also contribute to the pathogenesis of allergic diseases." (PMID 29375821, 2018). "Apart from the production of IL-35, regulatory T cells also produce IL-10 and TGF-β which involved in an immune-regulation for allergy by suppressing effector T cell response(s), inhibiting allergen-specific IgE production, and inducing IgG4 and/or IgA production in human after SIT." (PMID 26954254, 2016). "For example, B. longum BB536 is claimed to alleviating symptoms of allergy by promoting Th1 response, whereas B. longum ACTT15707 showed a strong induction of interleukin 10 (IL-10) and could help in the treatment and prevention of gastrointestinal infection." (PMID 27746766, 2016). "IL-10 and TGF-β secreted by Treg cells have a suppressive function for subtypes of other helper T cells and, currently, generating and maintaining allergen-specific Treg cells in the immunotherapy during allergy treatment are known to be important." (PMID 27403198, 2016). "It has been shown that Tregs secreting IL-10 play an important role in allergic diseases, independent of CD25+ Tregs." (PMID 27646403, 2016). "Moreover, ASC treatment increased anti-inflammatory cytokines, IL-10 and TGF-β, in the BALF and LLNs, which ultimately led to decreased lung eosinophil infiltration, goblet cell hyperplasia, allergy-specific Th2 cytokines, and Ig production." (PMID 26176545, 2015). "Indeed, IL-10 release by immune cells, which is enhanced by both NGF and BDNF in normal conditions, is dramatically reduced in cases of allergy." (PMID 24223945, 2013). "Both FOXP3+CD4+CD25+ regulatory T (Treg) cells and inducible IL-10- and TGF-β-producing type 1 Treg (Tr1) cells may prevent the development of allergic diseases and play a role in successful allergen-SIT and healthy immune response via several mechanisms." (PMID 22409879, 2012). "It is not unexpected that Th1 cytokines and IL-10 have a protective effect on allergy-related phenotypes." (PMID 23724228, 2011). "Bioactive bovine IL-10 could potentially be used for the prevention of inflammatory diseases as NEC and allergy in infant nutrion, or in immunomodulating diets for patients suffering from intestinal inflammatory disorders." (PMID 21464967, 2011). "c) Decreasing S100B levels in ADHD groups related to decreasing levels of IL-16, but increasing levels IL-10 (independent of age), - where IL-16 and IL-10 correlated with allergy sensitivity." (PMID 20509936, 2010). "Using a murine model of an OVA-induced allergy, we show that methylated ODN-A (2m-V1) and ODN-D (3m-V4) markedly reduce serum anti-OVA IgE, clinical symptoms, eosinophilic infiltration, and Th2/Th17 responses, while promoting splenic Treg expansion and IL-10 production." (PMID 40725003, 2025). "Interestingly, after exposure to milk, those with an “allergy” were shown to spike in IL-10, surpassing those without suspected allergy." (PMID 36059314, 2022). "Due to the small number of enrolled patients, we were unable to test whether the number of IL-10-producing Breg cells differed between patients with and without allergies." (PMID 34867940, 2021). "The authors found that the reduction of the allergic response was dependent on IL-10 producing follicular B cells (B220+ CD19+ CD23+ IgM+ CD40+ MHCIIhi), indicating that CpG-ODN-stimulated B cells have a role in promoting immune tolerance in the context of allergy." (PMID 33708195, 2021). "Parity between our results using specific knockout of T cell–derived IL-10 and global blockade of pulmonary IL-10 signaling suggest that CD4+ Teff cells are the functionally dominant IL-10–producing cells for limiting IFN-γ responses in the lungs in patients with HDM allergy." (PMID 31445933, 2020).
Allergy (continued). "YPFS has a certain effect on Th2-type cytokines such as (IL-4, IL-6, IL-10, and IL-17) and Th1 type cytokines such as (IFN-γ and tumor necrosis factor-α), and YPFS mainly exerts pharmacological effects such as immune regulation and anti-allergy and anti-inflammatory by acting on these cytokines." (PMID 31885639, 2019). "Thus, fermented B. rapa L. may suppress allergic reactions through the production of IFN-γ and IL-10 by immune cells." (PMID 31167991, 2019). "However, none of these markers uniquely defined all IL-10-producing B cells (B10), which were reported to participate in chronic inflammation and allergic disease." (PMID 28428789, 2017). "IL-10 levels in the PPG-TLR2 innate immune pathway were lower in the offspring from the mothers with allergies than those from the mothers without allergies (P = 0.006), in agreement with the observations in CD4+CD25+FOXP3+T cells and the FOXP3/LGA3 expression profiles for these groups." (PMID 27646403, 2016). "However, avoiding activation of the TLR-mediated immune pathway appears safer than a desensitization approach for preventing allergic disease development in the offspring of allergic pregnant women since the latter can up-regulate CD4+CD25+ T cells and IL-10 production in offspring." (PMID 27646403, 2016). "IL-4 promotes the development of Th2 cells and allergic inflammation so IL-4 increase may exacerbate ongoing allergy but can be suppressed by IL-10 and TGF-β regulatory cytokines; still further studies are needed to investigate B. integerrima influence on different types of allergy." (PMID 28031908, 2015). "IL-10 is a functional feedback regulator of immune responses that inhibits a wide range of inflammatory and immune responses, down regulates the expression of TH1 cytokines, inhibits TH2 and allergy responses, sustains the expansion of Treg cells and is known to reduce the severity of RA." (PMID 25950840, 2015). "In human memory CD4+ T cells, we also observed an increase in H3K4me3 and a decrease in H3K27me3 at the IL-10 promoter upon GSK3 inhibition, strengthening our suggestion that GSK3 inhibition may be a means of upregulating IL-10 production in autoimmune or allergic disease." (PMID 25627813, 2015). "Both IL-10 and TGF-β are immunosuppressive cytokines produced by a number of cell types, including the regulatory T cell subsets, and may therefore play a role in the prevention or control of allergic responses." (PMID 24067384, 2013). "As well as inducing the Th2/TFH2/TFH13 axis, the severity of IgE-mediated allergies has been associated with functional impairment of non-follicular [Treg (CXR5-FoxP3+IL-10+) and Tr-1 (CXCR5-FoxP3-IL-10+)] and follicular [TFR (CXCR5+ FoxP3+IL-10+)] regulatory CD4+ T cells." (PMID 37954580, 2023). "However, in studies in allergy which have supported an important role for B regs, some consensus seems to reside in a role for a Th2 cytokine mediated enhancement of Breg IL-10 production as an important mechanism of action-this has not been investigated in the studies described." (PMID 31827543, 2019). "Fifth, the influence of IL-4 combined with other genes (such as IL-6, IL-10, IL-17, IL-27, IFN-γ, etc.)or the environments on allergies has not been analyzed." (PMID 33834211, 2021). "In this study, hTMSCs secreted high amounts of IL-6 and IL-8, but not IL-10, TNF-α, or IFN-γ, irrespective of allergy state." (PMID 26376485, 2015). "Children with allergies had a lower number of PPG-stimulated CD4+CD25+FOXP3+T cells (P = 0.01), reduced FOXP3 expression in response to PPG and LPA (P = 0.02 and P = 0.01, respectively), and lower IL-10 production (P = 0.016), compared to the children without allergies." (PMID 27646403, 2016).
diabetes (347 papers, 2006 to 2026). "Haplotype analysis of IL10 gene polymorphism T/C (rs1800871) and A/G (rs1800896) in type 2 diabetes mellitus (T2DM) (n = 126), diabetic nephropathy (DN) patients (n = 75), and healthy individuals (controls) (n = 100)." (PMID 40936203, 2025). "STZ-induced diabetes was associated with a significant decrease in the anti- inflammatory cytokine IL-10 and an increase in the proinflammatory cytokines CXCL-1, IFN-γ, IL-6, IL-18, and IL-33." (PMID 40649891, 2025). "Gut microbiota were also implicated in these changes, emphasizing the IL-10–microbiome–immunity axis in diabetes pathogenesis." (PMID 40804870, 2025). "IL10 imbalance is linked to type 2 diabetes mellitus (T2DM) and also to renal hypertrophy, glomerular membrane thickening, and onset of diabetic nephropathy (DN)." (PMID 40936203, 2025). "The positive association between diabetes and IL-10 was mediated 14.7% by TNFR1, 8.1% by IL-6, and 13.1% by TNF-α independently." (PMID 41280118, 2025). "TNFR1 mediated 56.5% of the positive association between diabetes and IL-10 independently of IL-6, while IL-6 mediated 20.8% of the association independently of TNFR1." (PMID 41280118, 2025). "Metabolic diseases such as diabetes are associated with reduced IL-10, an anti-inflammatory cytokine produced by macrophages and lymphocytes." (PMID 38164478, 2024). "Our prior work showed IL-10-producing B regulatory cells (Bregs) protected B cell-specific TLR9-deficient NOD mice from diabetes." (PMID 38903498, 2024). "MSC-Exos treated mice showed recovery of diabetes associated pathologies with significantly reduced blood glucose, recovered body weight, increased IL-10 secretion and M2 polarized macrophages in the heart." (PMID 38390337, 2024). "In diabetes, associations between IL-8 and prolonged gastric emptying (odds ratio (OR) 1.07, p = 0.027) and between IL-10 and prolonged colonic transit (OR 29.99, p = 0.013) were seen." (PMID 37189645, 2023). "On the other hand, IL-10 can exhibit a pathogenic action at the beginning of the disease, and its local release can accelerate the onset and increase the prevalence of diabetes." (PMID 37189738, 2023). "In summary, we present a novel regulatory B cell subset, characterized by the expression of CD103, increased in NLRP6 deficiency and are potent TGFβ- and IL-10 producers, all of which delayed and prevented diabetes development." (PMID 36911699, 2023). "We showed that prolonged gastric emptying in diabetes was associated with increased serum levels of IL-8, while increased levels of IL-10 were associated with prolonged colonic transit time." (PMID 37189645, 2023). "For example, increased pro-inflammatory factors tumor necrosis factor-α (TNF-α), interleukin-10 (IL-10), and C-reactive proteins (CRPs) lead to an inflammatory response associated with neuropathy in diabetes." (PMID 36313015, 2022). "Recently, both increased and decreased IL-10 serum levels have been reported to be associated with diabetes and GDM." (PMID 36992770, 2022). "In this study, we investigated the role of interleukin 10 (IL-10) in the inhibition of diabetes in BDC2.5+ NOD mice by generating Il-10-deficient BDC2.5+ NOD mice (BDC2.5+Il-10-/- NOD mice)." (PMID 34394099, 2021). "Dysregulation of IL-6 and IL-10 are associated with increased risk of developing Type 2 Diabetes Mellitus (T2DM)." (PMID 33858419, 2021). "The STZ-induced mice that were treated with combined bacterial strains carrying plasmids encoding IL-4 and IL-10 showed lower incidence of diabetes and more preserved pancreatic islets than the mice that received the individual bacterial strains." (PMID 33604389, 2021). "Genetic polymorphism in IL-10 is of great clinical interest because IL-10 is an important cytokine which regulates inflammatory and immune responses in various pathological situations including diabetes." (PMID 30873205, 2019). "IL-10 has been shown to play a protective role in diabetes and decreased IL-10 level was associated with diabetes." (PMID 31164920, 2019).
diabetes (continued). "IL-10 also suppressed the induction and progression of autoimmune pathogenesis associated with diabetes." (PMID 31164920, 2019). "Previously, we reported that the susceptibility of DR+/+ rats to KRV triggered diabetes declines with age and is coincident with the temporal acquisition of an IL-10- and TGF-β-mediated immunoregulated state." (PMID 29293587, 2018). "This study aimed to investigate the association of plasma TNF-α, IL-6, and lL-10 levels and cytokine gene polymorphisms [TNF-α (-308 G→A), IL-6 (-174 C→G) and IL-10 (-1082 A→G, -819 T→C and -592 A→C)] in type 2 diabetes mellitus (T2DM) and obese patients." (PMID 28225860, 2017). "Last, levels of inflammatory cytokines IL-1β and TNF-α and anti-inflammatory cytokine IL-10 were detected in the plasma, since inflammation is a key pathogenic factor for diabetes consequence." (PMID 29296174, 2017). "Our results are in line with previous reports that delivering a pDNA encoding IL-10 to NOD mice early in the diabetogenic response leads to a prevention of overt diabetes." (PMID 25157497, 2014). "Age above the median (42 years) was associated with lower odds of elevated IL-10, self-reported high cholesterol and diabetes with higher odds of elevated TNF-α, and current ART use with lower odds of elevated TNF-α." (PMID 23987993, 2013). "In a logistic regression analysis after adjusting for age, sex, arterial hypertension, diabetes mellitus, hypercholesterolemia, and smoking habits, carriage of the IL10 -592A-allele was associated with an odds ratio of 0.65 (95% CI: 0.44-0.97) for RAO." (PMID 17438520, 2007). "Elevated levels of IL-10 or reduced levels of IFN-γ in individuals with diabetes may be associated with an increased risk of oral candidiasis." (PMID 39458293, 2024). "Moreover, IL-10 was previously reported as associated with preventing diabetes by restraining the insulitis and improving beta cell condition." (PMID 36091019, 2022). "IL-10 is an anti-inflammatory cytokine, which plays an important role in regulating the innate immune system, and has been associated with inflammatory-associated diseases such as obesity and diabetes." (PMID 36992770, 2022). "It is important to state that a previous study found that the induction of diabetes in animal models might induce mutations in the IL10 gene in some organs rather than others, resulting in alterations in the expression of IL10 in tissues." (PMID 36213511, 2022). "Hence, depletion of IL-10 in microglia significantly attenuated diabetes-associated cerebral atherosclerosis in mice." (PMID 35935990, 2022). "In these mice, splenic CD4+ T cells produced larger amounts of IL-10 which thus could be the cause of a significant delay in diabetes onset." (PMID 36389662, 2022). "For instance, previous studies have consistently reported that level of serum anti-inflammatory cytokine IL-10 is significantly associated with insulin sensitivity in young individuals, which may later develop towards type 2 diabetes mellitus or chronic pain." (PMID 31991875, 2020). "In fact, several studies have also reported the regulatory roles of T-helper cell cytokines in multiple low doses of streptozotocin (MLD-STZ) diabetes model, suggesting the pathogenic role of IL-17 and IL-1β and protective role of IL-6, IL-10, and IL-4 in MLD-STZ mice." (PMID 29317893, 2017). "In addition, low production of IL-10 has been associated with several cardiovascular risk factors, such as metabolic syndrome, insulin resistance and type 2 diabetes mellitus, and overweight-related sleep apnea." (PMID 25923658, 2015). "Analyses by multivariate linear regression adjusting for immuno-virologic and diabetes risk parameters showed weak associations of uncertain significance [log-sE-selectin (β = 0.07, p = 0.044), log-tPAI-1 (β = 0.09, p = 0.035), and log-IL-10 (β = 0.02, p = 0.037)]." (PMID 24587328, 2014). "Total and stratified analyses of the interleukin-10 polymorphisms on type 2 diabetes mellitus risk." (PMID 23805237, 2013).
diabetes (continued). "Finally, prevention of diabetes by injection of IL-10 expressing vector into NOD mice is associated with an increase in CD4+CD25+ regulatory T cells." (PMID 21716731, 2011). "In a logistic regression analysis, after adjusting for age, sex, arterial hypertension, hypercholesterolemia, diabetes mellitus, and smoking habits the presence of the IL10 -592A-allele was associated with an odds ratio of 0.65 for RAO, suggesting a protective effect against RAO." (PMID 17438520, 2007). "However, IL-10–deficient NOD mice are protected against diabetes." (PMID 35113966, 2022). "In addition, polymorphisms in the IL-10 gene increase diabetes risk." (PMID 36443718, 2022). "However, low levels of IL-10 have been considered as a risk factor of diabetes, which may also contribute to MI in diabetic patients." (PMID 31164920, 2019). "An association with IL-10 was investigated for a number of confounders and precision variables, and all significant variables (sex, age, statin treatment at randomization and history of diabetes) were included in the downstream analyses investigating the associations between SNPs and IL-10 levels." (PMID 26600159, 2015). "This study investigated the role of MyD88/IL-10 signaling in diabetes-induced systemic inflammation and hepatic gluconeogenesis." (PMID 41898743, 2026). "In the base model predicting IL-10, one year of age was associated with a 0.012 standard deviation increase, while having hypertension or CVD, diabetes, and cancer were each associated with a 0.181, 0.231, and 0.112 increase respectively." (PMID 41280118, 2025). "In another study, cholecalciferol supplementation at 40,000 IU/week for 24 weeks was associated with improvements in cutaneous microcirculation and peripheral neuropathy in patients with diabetes mellitus type 2, as well as increased IL-10." (PMID 39861482, 2025). "Diabetes increased IL-10, IL-17, IL-22, and TNF-α levels, and reduced IL-1β levels in the colon of diabetic mice compared to non-diabetic controls, without altering the content of IL-4, IL-6, and TGF- β1." (PMID 40496562, 2025). "Key variables (ferritin, IL-10, diabetes) were assigned scores based on their regression coefficients, with total scores mapped to predicted probabilities." (PMID 41426569, 2025). "IL-10 has also been shown to significantly reduce the incidence of diabetes and delay the onset of disease when administered daily and subcutaneously to NOD mice." (PMID 40299229, 2025). "Interleukins such as IL-1β, IL-6, and IL-10 emerge as central mediators in β-cell dysfunction, chronic inflammation, insulin resistance, and the progression of diabetes-related complications." (PMID 40804870, 2025). "For example, a 70-year-old patient with diabetes (score = 10), ferritin = 5,000 μg/L (score = 30), and IL-10 = 20 pg./mL (score = 20), the total score (60 points) corresponds to a 84.7% risk of treatment failure (95% confidence interval (CI): 65–92%)." (PMID 41426569, 2025). "Correlation anal is revealed significant associations between immune markers (CD14+, HLA-DR, IL-10, CD8+), clinical parameters (BMI, coronary heart disease, hypertension, diabetes), and behavioral factors (physical activity, smoking, alcohol)." (PMID 40218200, 2025). "APMB-specific significant positive correlations existed between the co-presence of diabetes and dialysis dependence, presence of diabetes and longer antibiotic duration, and presence of cardiac vegetation and elevated IL-10." (PMID 39966757, 2025). "In Type 1 diabetes mellitus (T1D) a significant increase in the expression of interleukin-10 (IL-10) and tumor necrosis factor-alpha (TNF-α) genes has been observed." (PMID 40299229, 2025). "The nomogram incorporated diabetes, ferritin, and IL-10, demonstrating robust calibration (Hosmer-Lemeshow p = 0.84; Brier score = 0.182) and discrimination (sensitivity = 71.4%, specificity = 70.0%)." (PMID 41426569, 2025).